OR10A2 (olfactory receptor family 10 subfamily A member 2)
Description:
Odorant receptor.
Synonyms: OR10A2P; OST363; OR11-82; OR11-86
Tractability: Antibody: UniProt places it where antibodies can reach, with medium confidence; UniProt predicts a signal peptide or a membrane-spanning region; its Gene Ontology location is reachable by antibodies, with medium confidence.
Gene: Protein-coding gene on chromosome 11 (6,863,057 to 6,874,717, forward strand). Ensembl gene ENSG00000170790.
Subcellular location: Cell membrane
Pathways (Reactome):
Sensory Perception: Expression and translocation of olfactory receptors
Gene Ontology:
Molecular function: olfactory receptor activity; G protein-coupled receptor activity
Biological process: detection of chemical stimulus involved in sensory perception of smell; G protein-coupled receptor signaling pathway
Cellular component: plasma membrane; membrane
Genetic constraint (gnomAD): Loss-of-function variants: 15 observed, 14.27 expected, observed/expected ratio (o/e) 1.05, 90% interval 0.7 to 1.61. The upper end of that interval is the gene's LOEUF score, 1.61, which puts it in group 6 of 6, group 1 being the genes least tolerant of losing a copy. Missense variants: 343 observed, 371.18 expected, observed/expected ratio (o/e) 0.92, 90% interval 0.85 to 1.01. Synonymous variants: 145 observed, 147.3 expected, observed/expected ratio (o/e) 0.98, 90% interval 0.86 to 1.13.
Homologues: Orthologues: chimpanzee OR10A2 (99% identical), dog OR10A5F (94% identical), dog OR10A5 (94% identical), dog OR10A5D (93% identical), dog OR10A5E (93% identical), mouse Or10a5 (92% identical), rat Or10a5 (90% identical), mouse Or10a2 (89% identical), rat Or10a2 (88% identical). Paralogues in human: OR10A5 (96% identical), OR10A4 (73% identical), OR10A7 (60% identical), OR10A3 (57% identical), OR10A6 (54% identical), OR10C1 (52% identical), OR10P1 (48% identical), OR10H1 (48% identical), OR2C3 (48% identical), OR10AG1 (47% identical), OR10H5 (47% identical), OR6Y1 (47% identical), and 80 more.